ABCC4 (ATP binding cassette subfamily C member 4 (PEL blood group))
Diseases named in the same sentence as ABCC4 in open-access papers (continued):
Sharing a sentence is not in itself a finding about the gene and the disease.
ovarian carcinoma (15 papers, 2010 to 2023). A malignant neoplasm originating from the surface ovarian epithelium. "Frequent overexpression of ABCC4 has been observed in primary neuroblastoma and ovarian cancer and is significantly associated with a poor clinical prognosis." (PMID 35869071, 2022). "ABCC4 has also been implicated in cancer cell proliferation in leukemia, gastric cancer, lung cancer, renal cancer, ovarian cancer, and pancreatic cancer." (PMID 33081264, 2020). "In ovarian cancer (OC), Seborova et al54 indicated that downregulation of ABCC4, called the “Multidrug resistance protein 4,” was associated with the best sensitivity to chemotherapy and time to progression." (PMID 32250047, 2020). "However, in epithelial ovarian cancer, ABCC4 was associated with proliferation, migration, and invasion." (PMID 33081264, 2020). "Furthermore, ABCC1 is associated with higher tumor grade, and ABCC4 with reduced progression-free survival of patients with ovarian cancer." (PMID 28674494, 2017). "In a study that included 127 patients with ovarian cancer, ABCC4 (MRP4) was associated with shorter progression-free survival." (PMID 28674494, 2017). "Epithelial ovarian cancer tissues have been shown to express other ABC transporters including, ABCC3 (MRP3), ABCC4 (MRP4), ABCB1 as well as other membrane transporters." (PMID 37838788, 2023). "Oxaliplatin resistant ovarian cancer cells have been shown to overexpress ABCC1 and ABCC4." (PMID 24124770, 2013).
colorectal cancer (13 papers, 2014 to 2024). A primary or metastatic malignant neoplasm that affects the colon or rectum. "Risk estimates for the involvement of polymorphisms in COX-2/HPGD/SLCO2A1/ABCC4 genes in colorectal cancer onset stratified by sex, smoking habits and body mass index." (PMID 24694755, 2014). "Genotype frequencies among cases and controls and risk estimates for the involvement of COX-2/HPGD/SLCO2A1/ABCC4 polymorphisms in colorectal cancer onset." (PMID 24694755, 2014). "We demonstrated that the pharmacological inhibition of ABCC4 increases the migratory rate and invasive protrusion formation in colorectal cancer (CRC)." (PMID 33261018, 2020). "It was demonstrated that the rs3742106 polymorphism in the 3′-UTR that enhances miR-3190-5p-mediated inhibition of ABCC4 expression is significantly related to the increased efficacy of 5-FU/capecitabine-based chemotherapy in colorectal cancer." (PMID 29401721, 2018). "Lentivirus-mediated small hairpin RNA was applied to inhibit ABCC4 expression in colorectal carcinoma cell line RKO, and investigate the radiosensitivity in xenograft model." (PMID 24454870, 2014).
neuroblastoma (12 papers, 2012 to 2022). Neuroblastoma (NB) is the most common solid, extracranial childhood tumor. "ABCC1, ABCC3, and ABCC4 have been suggested to be linked with tumor growth and prognosis in neuroblastoma." (PMID 34650973, 2021). "This contrasts with a study investigating the role of these transporters in neuroblastoma, where ABCC4 was more associated with proliferation and ABCC1 with migration." (PMID 33081264, 2020). "Increased MRP4/ABCC4 levels have been significantly associated with poor clinical outcome in neuroblastoma." (PMID 25301721, 2014). "More importantly, ABCC4 expression in primary neuroblastoma is strongly associated with reduced event-free survival and overall survival and multivariate analysis revealed that ABCC4 expression retained prognostic significance following adjustment for tumor stage, age, and MYCN amplification." (PMID 23267433, 2012). "Recently, the inhibition of ABCC4 is confirmed as a potential cure for neuroblastoma by inhibiting tumor proliferation and sensitizing to chemotherapeutic drug." (PMID 33014785, 2020). "In a subsequent study, the same group further investigated ABCC4, to strengthen the link between its up-regulation and neuroblastoma tumor biology." (PMID 32587767, 2020). "It has been reported that knockdown of ABCC1 and ABCC4 decreases sphere formation efficiency of neuroblastoma cells, suggestive of decreased stemness." (PMID 27171227, 2016). "In this review, we examine the potential role of ABCC4 in the malignant phenotype of neuroblastoma and other cancers and consider the potential benefits of targeting the MRP4 protein." (PMID 23267433, 2012). "Studies currently in progress involving cross breeding between MYCN transgenic mice and Abcc4 gene knockout mice will further assess the biological impact of MRP4 in neuroblastoma development, progression, and treatment response." (PMID 23267433, 2012). "HepG2 cells transfected with the human ABCC4 plasmid showed enhanced resistance to irinotecan, topotecan, and cyclophosphamide, all of which are used in neuroblastoma treatment or are in trial for use." (PMID 23267433, 2012). "In addition, inhibition of ABCC4 attenuates the proliferation of neuroblastoma cells and sensitizes tumors to irinotecan treatment." (PMID 34244494, 2021). "Furthermore, expression of ABCC4 was determined in primary untreated neuroblastoma tumors indicating that ABCC4 expression levels were independent of prior treatment exposure." (PMID 23267433, 2012). "Of these, ABC subfamily C member 1 (ABCC1), ABCC3, and ABCC4 are direct transcriptional targets of MYCN and expression levels of each of these genes are independent prognostic factors for neuroblastoma." (PMID 23267433, 2012). "Studies on neuroblastoma (a rare childhood cancer) have confirmed that both ABCC1 and ABCC4 play an important physiological role in its development, independent of their role in multidrug resistance, affecting cellular proliferation, migration, and differentiation." (PMID 33081264, 2020).
pancreatic cancer (11 papers, 2012 to 2024). "Similarly, in pancreatic cancer, ABCC4 was associated with proliferation." (PMID 33081264, 2020). "Furthermore, it was shown that depletion or inhibition of ABCC4 can inhibit cell growth of neuroblastoma cells and reduce proliferation of pancreatic cancer, not only increasing sensitivity to chemotherapeutics but also presenting cytostatic abilities." (PMID 29401721, 2018). "In addition, CBX3 and ABCC4 are promising therapeutic targets in osteosarcoma and pancreatic cancer, respectively." (PMID 26179909, 2015). "Although the expression profile and function of ABCC4 in OSCC remain unclear, this gene is a promising target for treatment of pancreatic cancer." (PMID 26179909, 2015).
colon carcinoma (8 papers, 2011 to 2020). "To identify the ABC transporter genes regulated by c-MYC in human colon cancer cells, we investigated the effect of c-MYC knockdown on MDR1, MRP1, ABCB5, ABCC4 and ABCC5 expression levels, which are closely involved in the resistance to chemotherapeutic agents including 5-FU 17–23." (PMID 25689483, 2015). "However, no direct co-expression for ABCC4 with these enzymes or SLCO2A1 was observed in our study, which was in contrast to previous data from a colon cancer study." (PMID 30131693, 2018).
gastric cancer (8 papers, 2016 to 2022). A primary or metastatic malignant neoplasm involving the stomach. "For instance, NEAT1 functions as a sponge for miR-365a-3p to facilitate gastric cancer progression through targeting ABCC4; furthermore, NEAT1 sponges miR-129 to regulate renal fibrosis via modulating coll I." (PMID 34040522, 2021). "Long Non-Coding RNA NEAT1 sponges miR-365a-3p to enhance progression of gastric cancer by tarheting ABCC4." (PMID 34789263, 2021). "For example, the functions of ABCC4 have been reported in human gastric cancer, where ABCC4 expression is highly expressed in multiple types of gastric cancer cells and is even more conspicuous in the drug-resistant gastric cancer cells." (PMID 30643796, 2018).
glioma (8 papers, 2010 to 2023). A benign or malignant brain and spinal cord tumor that arises from glial cells (astrocytes, oligodendrocytes, ependymal cells). "In GBM and lower grade glioma, there is an increase in MRP4/ABCC4 expression." (PMID 36765904, 2023). "Likewise, the ABC transporters, MRP1 (ABCC1), MRP3 (ABCC3), and MRP4 (ABCC4), are highly expressed in glioma cells." (PMID 35740330, 2022). "Changes in MRP4/ABCC4 expression may be specific to gliomas." (PMID 36765904, 2023). "ABCC4 and ABCC5 mRNA overexpression and immunostaining has been observed in the glioma cells of astrocytic tumors and in the astrocytic portions of oligoastrocytomas." (PMID 31878061, 2019). "ABCB1/P-gp, ABCG2/BCRP, ABCC1/MRP1, ABCC4/MRP4, and ABCC5/MRP5 up-regulation has been observed in glioma cells at the mRNA and/or protein level; moreover, MRP3 de novo protein expression has also been detected in high grade gliomas (detailed below)." (PMID 31878061, 2019). "We investigated levels of multiple drug resistance-related genes in U87 and primary glioma cells, including genes related to drug efflux (ABCB1, ABCC1, ABCC2, ABCC4, ABCG2, ATM), DNA damage repair (MGMT) and stemness (CD133)." (PMID 27486877, 2016). "ABCC3 is expressed more in differentiated glioma cells and regulates multidrug resistance, while ABCB1 and ABCC4 are important multidrug resistance factors." (PMID 25605243, 2015).
lung cancer (8 papers, 2007 to 2023). A malignant neoplasm involving the lung. "Diseases associated with ABCC4 include lung cancer and hemostasis is involved in its associated pathways." (PMID 27437769, 2016). "Further, recent study associated SNP rs9524885 in MRP4/ABCC4 (as well as rs2756109 in MRP2/ABCC2) with pain in nonsmall-cell lung cancer patients." (PMID 23766564, 2013). "In addition, a study of 400 lung cancer patients found that the glutathione peroxidase 7 (GPX-7) gene and ABCC4 SNPs were associated with peripheral neuropathy following chemotherapy, attributing to the effect of SNP on gene expression." (PMID 37563730, 2023). "ABCC4 mRNA was highly expressed in lung cancer tissue and lung cancer cell lines." (PMID 27437769, 2016).
acute myeloid leukemia (7 papers, 2012 to 2025). Acute myeloid leukemia (AML) is a group of neoplasms arising from precursor cells committed to the myeloid cell-line differentiation. "ABCC4 is a chemotherapeutic drug exporter highly expressed in acute myeloid leukemia." (PMID 29146910, 2017).
diabetes (7 papers, 2015 to 2025). "Future studies are warranted to elucidate the role of ABCC4 in metabolic disorders such as insulin resistance, obesity, diabetes and hyperlipidemia." (PMID 41038958, 2025). "The Gln allele of the CREBRF p.Arg457Gln variant associates with increased BMI but reduced risk of diabetes, the Ser allele of the IL37 p.Asn182Ser variant with gout, and the Western Polynesian-specific Leu allele of the ABCC4 p.Pro1036Leu variant with gout." (PMID 34719381, 2021). "Notably, research on ABCC4 knockout (ABCC4−/−) mice has established a link between the absence of ABCC4 and the development of obesity and diabetes." (PMID 39717760, 2024).
leukemia (7 papers, 2012 to 2025). A malignant (clonal) hematologic disorder, involving hematopoietic stem cells and characterized by the presence of primitive or atypical myeloid or lymphoid cells in the bone marrow and the blood. "Much attention has been focused on the association between ABCC4 gene and leukemia outcomes, as well as platelet activation." (PMID 41038958, 2025). "Altogether, these findings show that MRP4/ABCC4 has a relevant role in tumor growth and apoptosis and in the eradication of LSCs, providing the basis for a novel promising target in leukemia therapy." (PMID 25301721, 2014). "We previously demonstrated that besides playing a role in drug-resistant leukemia cell lines, multidrug resistance protein 4 (MRP4/ABCC4) regulates leukemia cell proliferation and differentiation through the endogenous MRP4/ABCC4 substrate, cAMP." (PMID 25301721, 2014). "Indeed, previously we demonstrated that besides playing a role in drug-resistant leukemia cell lines, MRP4/ABCC4 regulates leukemia cell proliferation and differentiation through the endogenous MRP4/ABCC4 substrate, cAMP." (PMID 25301721, 2014).
leukopenia (7 papers, 2018 to 2023). "Meanwhile, ABCC4 c.2128G > A (rs3765534) carriers experienced a significant increase in the DNA-TG to 6-MP dose ratio, which was associated with a high risk of leukopenia." (PMID 36238550, 2022). "Evidence from studies in ALL children indicates significant associations between SLC29A1, SLC28A2, SLC28A3 and ABCC4 variants and one or more of the hematological toxicity manifestations (neutropenia, agranulocytosis and leukopenia)." (PMID 36015138, 2022). "Data from a study in breast cancer patients show that ABCC4 expression is associated with gastrointestinal toxicity and leukopenia." (PMID 36015138, 2022). "ABCC4 Glu757Lys showed an association with leukopenia, and rs2834826 located upstream of RUNX1 showed an association in the conditional analysis on NUDT15 Arg139Cys." (PMID 29923122, 2018). "In addition, some studies have found that a mutation in ABCC4 (rs9561778) encoding MRP4 is significantly correlated with CYC-induced ADR (gastrointestinal toxicity and leukopenia/neutropenia)." (PMID 35935867, 2022). "ATP-binding cassette subfamily C member 4 (ABCC4), also known as multidrug-resistance protein 4 (MRP4), is associated with thiopurine metabolism; its genetic variant rs3765534 (p.Glu757Lys) was reported to be associated with leukopenia in the Japanese." (PMID 29923122, 2018). "No additional SNPs were found in the conditional GWAS; therefore, we included the genotype of NUDT15 codon 139 or NUDT15 haplotype, ABCC4, and RUNX1 in the logistic regression models to predict thiopurine-induced severe leukopenia and alopecia." (PMID 29923122, 2018).
gout (6 papers, 2016 to 2024). A condition characterized by painful swelling of the joints, which is caused by deposition of urate crystals. "The gout symptoms in this patient may have been caused by dysfunction of the ABCC4 apical efflux transporter." (PMID 35406626, 2022). "Following these analyses, two SNVs in the coding regions of two gout-associated genes (CPT2 and ABCC4) were retained." (PMID 35372350, 2022).
neutropenia (6 papers, 2022 to 2025). A decrease in the number of neutrophils found in the blood. "For this reason, the presence of missense SNP in ABCG2, concomitant with other variants in renal drug transporters (SLC29A1 and ABCC4) in heterozygous, could affect the clinical drug efficacy in terms of risk of neutropenia." (PMID 39508043, 2024). "It is known that patients with rs11568658 in ABCC4 and kidney transplant may have an increased risk of neutropenia when treated with valganciclovir compared to patients with WT." (PMID 39508043, 2024). "ABCC4, SLC19A1, SLC28A3, SLC29A1, SLCO1B1 genetic variants were associated with thiopurine-related toxicities; neutropenia, hepatotoxicity and treatment interruption, especially in Asians." (PMID 36015138, 2022).
Obesity (6 papers, 2019 to 2025). Accumulation of substantial excess body fat. "Additionally, ABCC4-knockout mice exhibit typical obesity phenotypes, including adipocyte hypertrophy and insulin resistance, through the disruption of cAMP transport." (PMID 40658709, 2025). "Here, we found that some DMR genes are obesity genes or related to the former which have been studied by genomic and genome-wide association study (GWAS) methods, for example, FTO, PCSK5, PCSK6, NTRK2, ABCC4, TXNIP and RPS6KA2." (PMID 31637123, 2019).
acute lymphoblastic leukemia (5 papers, 2014 to 2025). Leukemia with an acute onset, characterized by the presence of lymphoblasts in the bone marrow and the peripheral blood. "It has been reported that ABCC1, ABCC2, ABCC3, ABCC4, ABCC5 and ABCC6 play a significant role in MDR mediated non-small cell lung cancer (NSCLC), breast cancer, prostate cancer, colorectal cancer, ovarian cancer and acute lymphoblastic leukemia (ALL)." (PMID 25191874, 2014).
hepatocellular carcinoma (5 papers, 2012 to 2022). A malignant tumor that arises from hepatocytes. "For example, ABCC4 was reported to be regulated by miR-125a and miR-125b in hepatocellular carcinoma." (PMID 35753353, 2022).
asthma (4 papers, 2017 to 2023). "We investigated the potential associations between ABCC4 gene polymorphisms and asthma phenotype." (PMID 28659663, 2017). "Therefore, we investigated the potential associations between asthma and ABCC4 polymorphisms in a Korean population." (PMID 28659663, 2017). "We confirmed the expression of ABCC4 in human airway epithelial cells and its function in the context of regulating immune responses relevant in asthma and chronic respiratory disease." (PMID 34666750, 2021). "In the present study, we selected two SNPs within the ABCC4 gene to examine their potential roles in asthma pathogenesis based on their relationships with eicosanoid, sphingolipid metabolites, and proinflammatory cytokines." (PMID 28659663, 2017). "The present findings further suggest that ABCC4 represents a new potential target of asthma therapy." (PMID 28659663, 2017). "In asthma and COPD patient overexpresses, ABCC4 suggests that the steroid causes effects on its upregulation." (PMID 28900313, 2017). "Therefore, ABCC4 variants may also play an important role in the pathogenesis of asthma." (PMID 28659663, 2017). "There is little evidence regarding associations of ABCC4 polymorphisms with asthma in Korean patients." (PMID 28659663, 2017). "Therefore, ABCC4 may play an important role in inflammatory diseases, particularly in asthma, by regulating the intracellular concentration of cAMP." (PMID 28659663, 2017).
non-small cell lung carcinoma (4 papers, 2014 to 2019). A group of at least three distinct histological types of lung cancer, including non-small cell squamous cell carcinoma, adenocarcinoma, and large cell carcinoma. "In a human candidate gene approach study, ABCC4 rs9524885 has been associated with reduced pain among patients with non-small cell lung cancer." (PMID 31196165, 2019).
T-cell lymphoma (4 papers, 2018 to 2024). "IL-13 promoted the expression of ABCC4, leading to increased resistance of NK/T-cell lymphoma cells to asparaginase." (PMID 38365716, 2024). "We first revealed that IL-13 promoted NK/T-cell lymphoma cells chemotherapy resistance to adriamycin (ADM) by increasing ABCC4 expression." (PMID 30643796, 2018). "Recently, a study has shown that overexpression of ABCC4 is determined in human NK/T-cell lymphoma cells and regulates chemotherapy sensitivity to epirubicin (EPI) and cisplatin (DDP) in YTS cells." (PMID 30643796, 2018). "Meanwhile,IL-6, IL-10, and IL13 mediate ABCC4 resistance in T-cell lymphoma." (PMID 38178117, 2024). "Our findings concluded that IL-13 inhibited chemotherapy sensitivity of NK/T-cell lymphoma cells by regulating ABCC4, disrupting which may effectively improve the therapy protocols against resistant NK/T-cell lymphoma." (PMID 30643796, 2018). "Moreover, ABCC4 protein expression was also increased in NK/T-cell lymphoma YTS cells compared to the normal NK cells." (PMID 30643796, 2018). "Inhibition of ABCC4 may effectively improve the treatment of drug-resistant NK/T-cell lymphoma." (PMID 38365716, 2024). "ABCC4 and ABCG4 were significantly up-regulated in human NK/T cell lymphoma YTS and SNK-6 cells compared with normal NK cells." (PMID 38178117, 2024). "Based on gene expression regulation technology, overexpression of ABCC4 and ABCG4 can induce epirubicin (EPI) and cisplatin (DDP) resistance in human NK/ T cell lymphoma YTS cells and reduce cell apoptosis." (PMID 38178117, 2024).
breast tumors (3 papers, 2016 to 2020). "ABCC4 expression is similarly upregulated in chemotherapy-treated breast tumors compared to noncancerous tissue, and ABCC4 polymorphisms are linked with the response to aromatase inhibitors for estrogen-receptor-positive breast cancer." (PMID 33081264, 2020).